CTNNA3 (catenin alpha 3)
Diseases named in the same sentence as CTNNA3 in open-access papers (continued):
Sharing a sentence is not in itself a finding about the gene and the disease.
cytomegalovirus infection (1 paper, 2021). A herpesvirus infection caused by Cytomegalovirus. "Other similar GE interplay are those of FK Binding Protein Prolyl Isomerase 5 (FKBP5) and childhood trauma, AKT-8 retrovirus Serine/Threonine Kinase 1 (AKT1) and cannabis use, and Catenin Alpha 3 (CTNNA3) and cytomegalovirus infection in utero." (PMID 34829493, 2021).
dementia (1 paper, 2022). Loss of intellectual abilities interfering with an individual's social and occupational functions. "Fluctuating ‘expression levels’ of other KRs—such as CTNNA3 and JUN—in various brain parts in of people with NDs hints at nature of their contribution in progression of dementia." (PMID 35327643, 2022).
infertility disorder (1 paper, 2025). Inability to conceive for at least one year after trying and having unprotected sex. "A recent study reported the region of OAR25 close to the genes CTNNA3 and LRRTM3 as being prone to escape reprogramming and a potential candidate for transgenerational epigenetic inheritance, suggesting a potential genetic overlap between brain and infertility disorders." (PMID 40678382, 2025).
influenza (1 paper, 2024). An acute viral infection of the respiratory tract, occurring in isolated cases, in epidemics, or in pandemics; it is caused by serologically different strains of viruses (influenzaviruses) designated A, B, and C, has a 3-day incubation period, and usually lasts for 3 to 10 days. "Two proteins associated with influenza (LIF, KRT19 (which was also related to HHVs)) and one protein associated with skin and subcutaneous infections (CTNNA3) remained statistically significant at P < 0.05 after FDR correction." (PMID 39143319, 2024).
Intellectual disability (1 paper, 2014). "We identified a compound heterozygous deletion intersecting the CTNNA3 gene, encoding αT-catenin, in a proband with ASD and moderate intellectual disability." (PMID 25050139, 2014).
late-onset Alzheimers disease (1 paper, 2014). This is the most common form of the disease, which happens to people age 65 and older. "Other genes mapping in the deleted region, including DNAJC12 (MIM 606060), HERC4 (MIM 609248), PBLD (MIM 612189), HNRNPH3 (MIM 602324), RUFY2 (MIM 610328), STOX1 (MIM 609397), and CTNNA3 (MIM 607667), have been linked to late-onset Alzheimer’s disease (AD6; MIM 605526)." (PMID 24297458, 2014).
mastitis (1 paper, 2025). Inflammation of breast tissue during lactation or postpartum due to an obstructed duct or infection. "These included genes and QTLs related to somatic cell count and mastitis (CACNA2D1, SEMA5A, NEGR1, PTK2B, CTNNA3), gastrointestinal parasites (PTK2B), and various viral or bacterial diseases." (PMID 41273432, 2025).
Miscarriage (1 paper, 2015). A pregnancy that ends at a stage in which the fetus is incapable of surviving on its own, defined as the spontaneous loss of a fetus before the 22th week of pregnancy. "The remaining genes assayed had either very low or no expression in cultured chorionic villi from controls (PARK, LIPC, CTNNA3, EGFL6, GPM6B, RAB9A, POU6F2 and C7orf10) and were not assessed in miscarriages." (PMID 25674159, 2015).
neuroblastoma (1 paper, 2019). Neuroblastoma (NB) is the most common solid, extracranial childhood tumor. "We found that CTNNA1 and CTNNA2 had higher expressions, while CTNNA3 had consistently lower expression in both Wolf and Seeger datasets from patients with neuroblastoma." (PMID 31489113, 2019).
nicotine dependence (1 paper, 2021). Physical and psychological dependence on nicotine. "Multiple GWAS have revealed that CTNNA3 is a gene with clusters of SNPs associated with nicotine dependence." (PMID 34417442, 2021).
Obesity (1 paper, 2022). Accumulation of substantial excess body fat. "DNA methylation change of 15 imprinted genes induced by HFD feeding was observed, including Magel2, Ctnna3, Gab1, and L3mbtl1, that are reported to be linked to the pathogenesis of obesity, high cognitive processes in adulthood, circadian machinery, and growth and development of embryos." (PMID 35458198, 2022).
osteosarcoma (1 paper, 2022). A usually aggressive malignant bone-forming mesenchymal neoplasm, predominantly affecting adolescents and young adults. "Among them, CTNNA3 was reported as a tumor suppressor in HCC before and the same as DLG2 in osteosarcoma." (PMID 35321246, 2022).
Parkinson disease (1 paper, 2018). A progressive degenerative disorder of the central nervous system characterized by loss of dopamine producing neurons in the substantia nigra and the presence of Lewy bodies in the substantia nigra and locus coeruleus. "STK32B and CTNNA3 are two protein-coding genes, but the current study has not found any association with pathogenic pathways of Parkinson's disease." (PMID 29899728, 2018).
Patent ductus arteriosus (1 paper, 2023). In utero, the ductus arteriosus (DA) serves to divert ventricular output away from the lungs and toward the placenta by connecting the main pulmonary artery to the descending aorta. "In case 23, the LP variant of CTNNA3 was identified in the fetus with patent ductus arteriosus, but the transmitting mother was not an affected individual." (PMID 38318287, 2023).
polycystic kidney (1 paper, 2013). "Case 5 carried CTNNA3 and ACTR3B duplication, and exhibited open spina bifida, kidney agenesis and polycystic kidney phenotype." (PMID 23349908, 2013).
retinal degeneration (1 paper, 2021). Degeneration of the retina. "Whether in the overall or subgroup analysis (age > 60 years old, smoking, drinking, male, BMI > 24, and no retinal degeneration), CTNNA3-rs7914287 can increase the T2D risk under multiple genetic models among participants." (PMID 34717601, 2021). "Combined with the results of this study, CTNNA3-rs7914287 can significantly increase the risk of T2D participants and may not be affected by retinal degeneration or not." (PMID 34717601, 2021).
Sinus bradycardia (1 paper, 2021). Bradycardia related to a mean resting sinus rate of less than 50 beats per minute. "The result of gene prioritization analysis showed CTNNA3 was strongly correlated with sinus bradycardia, hinting it was a susceptibility gene of this ADR." (PMID 33914752, 2021). "CTNNA3 showed relatively strong correlation with sinus bradycardia, and this correlation might shed light on the association study of sinus bradycardia induced by SGAs." (PMID 33914752, 2021). "Interestingly, CTNNA3, having a strong correlation with sinus bradycardia backed up by our previous analysis, also interacted with DLG2 through circumstantial evidences." (PMID 33914752, 2021).
tauopathy (1 paper, 2024). Neurodegenerative disorders involving deposition of abnormal tau protein isoforms (tau proteins) in neurons and glial cells in the brain. "In contrast to the amyloid-β models, the Cst7+ population was very limited in the P301S tauopathy mouse model, and we could barely detect Ctnna3+ microglia in this model." (PMID 39592224, 2024).
tumor (17 papers, 2010 to 2025). "We found that CTNNA3 overexpression decreased tumor growth and miR-425 promoted tumor growth in vivo." (PMID 26882563, 2016). "The tumor suppressor function of CTNNA3 and the oncogenic function of miR-425 were further confirmed in HCC cell xenograft in nude mice." (PMID 26882563, 2016). "Notably, three members from the catenin super family, CTNNA1, CTNNA2, CTNNA3, were found to be dysregulated in tumor tissues." (PMID 36361574, 2022). "However, we corroborated the tumor-suppressive roles of insertions in Adk and Zbtb20 and in Nipbl, Pdlim5, Ppp1r12a, Tnrc6b, Brd4, Cul3, Ctnna3, Elavl1, Gphn, Nfia, Ptpn12, Taok3, and Rasa1." (PMID 33435458, 2021). "Here, we identified that a cell-cell adhesion gene, CTNNA3, is a tumor suppressor in HCC." (PMID 26882563, 2016). "Moreover the CTNNA3 gene contains a fragile site of potential interest in terms of genomic instability as there is evidence suggesting that it may function as a tumour suppressor." (PMID 21364586, 2011). "Among these were genes with tumor-suppressive activities such as CUL2, CTNNA3, and RNF8 (ST2B)." (PMID 40723280, 2025). "Worth to note, CNAs of 37 genes were exclusively found in G3 tumours such as WNT7B (4 gains), BAD (3 gains), WEGFB (3 gains) and HDAC2 (3 losses) in respect to 65 CNA genes exclusively presented in G1 tumours, such as GRB2 (5 losses) and FGF21, STAT3, CTNNA3 and DVL3 with 3 losses each." (PMID 28486536, 2017). "Moreover, miR-425 promotes the tumor growth of the HCC cell xenograft in nude mice, while CTNNA3 suppresses the growth." (PMID 26882563, 2016). "The aneuploidic increases in copy number of genes that may promote tumor formation, including ARHGAP26, GRB10, DDHD2, FGFR1, CTNNA3, PTPN1 and MLLT1 in the apparently stable and karyotypically normal lines HS293 and HS401, are cause for concern." (PMID 20428235, 2010). "The study of CTNNA3 and AFDN in skeletal muscle has not been reported, but there are many studies on them in tumor cells, mostly related to tumor cell proliferation and migration." (PMID 35484498, 2022).
cancer (15 papers, 2010 to 2025). A tumor composed of atypical neoplastic, often pleomorphic cells that invade other tissues. "And some identified 3′-UTR piSNV-affected genes, such as SLC6A11, NUDCD2, CTNNA3, RAB3C, and AJAP1, are well-studied cancer/disease related genes with a high deleterious mutation rate." (PMID 35654793, 2022). "CTNNA3 and TUSC3, which have also been cited as candidate TSGs for the same reason, could also have their status as TSG re-evaluated in light of our results, given that for each of these genes we have identified a number of cancer-free adult individuals with exon-disrupting deletions." (PMID 20195527, 2010). "Therefore, we investigated expression of MMP-9 in CTNNA3 knockdown cells, CTNNA3 overexpression cells and control cells with and without 12-O-tetradecanoylphorbol- 13-Acetate (TPA) treatment, which is an activator of protein kinase C that can promote cancer cell invasion via MMP-9 induction." (PMID 26882563, 2016).
heart disease (3 papers, 2016 to 2022). "For controls, CTNNA3 were found to be associated with Alzheimer and heart disease." (PMID 27168765, 2016).
neurodegenerative disease (1 paper, 2025). A disorder of the central nervous system characterized by gradual and progressive loss of neural tissue and neurologic function. "Similarly, ankyrin repeat domain 30B like (ANKRD30BL, 2q21.2), catenin alpha 3 (CTNNA3, 10q21.3), and eukaryotic translation initiation factor 4 gamma 3 (EIF4G3, 1p36.12), all previously implicated in neurodegenerative diseases, were also found to undergo sex‐specific RNA editing." (PMID 40631452, 2025).
CTNNA3 also shares sentences with these, for which no sentence is quoted: autism spectrum disorder (3 papers); cardiac arrhythmia (3); psychiatric disorder (3); arrhythmogenic right ventricular dysplasia, familial 13 (2); glioma (2); myopathies (2); neuroepithelial tumor (2); occupational asthma (2); schwannoma (2); airway hyperresponsiveness (1); amyotrophic lateral sclerosis (1); Aphasia (1); Arrhythmia (1); atrial fibrillation (1); attention deficit-hyperactivity disorder (1); Autoimmunity (1); bacterial diseases (1); bipolar disorder (1); brain disorder (1); capillary malformation (1); Cardio-cutaneous syndromes (1); cataract (1); colon cancer (1); diabetes (1); dysembryoplastic neuroepithelial tumor (1); eating disorder (1); epilepsy (1); essential tremor (1); extraventricular neurocytoma (1); food allergy (1).
A further 21 diseases each share a sentence with CTNNA3 in 1 paper.